MTOR (mechanistic target of rapamycin kinase)
Diseases named in the same sentence as MTOR in open-access papers (continued):
Sharing a sentence is not in itself a finding about the gene and the disease.
glioblastoma (continued). "This was due to the fact that sarcomas frequently show activation of PI3K/Akt/mTOR signaling and dual PI3K/mTOR inhibitors sensitize neuroblastoma and glioblastoma cells to DOX-induced apoptosis." (PMID 23300809, 2012). "Very interestingly, ribosomal protein S6 (RPS6) in the mTOR signaling was observed to be highly phosphorylated upon this input in human glioblastoma initiating cells." (PMID 22912867, 2012). "mTOR activity (as assessed by the abundance of p-rpS6) was significantly higher in glioblastomas compared to anaplastic astrocytomas, while there was only a trend for higher proliferation (Ki67) in these tumors." (PMID 22825389, 2012). "Increased SSAT expression was associated with apoptosis in the glioblastoma cells as demonstrated by decreased expression of anti-apoptosis-related signaling proteins AKT and mTOR." (PMID 22179681, 2012). "These preclinical results have been critical to planning the numerous clinical trials that have been performed with mTOR inhibitors in glioblastoma." (PMID 22530121, 2012). "In mesothelioma AXL-mediated invasiveness involves the PI3K/AKT/mTOR pathway, a pathway that is currently targeted in glioblastoma early drug development." (PMID 23077658, 2012). "The glioblastomas also showed significantly greater heterogeneity of intercapillary distances, larger diffusion-limited tissue fractions, significantly higher mTOR activity and a trend for higher proliferation rates." (PMID 22825389, 2012). "In the tumor development, mTOR signaling has been shown to enhance the survival of dormant tumor cells and maintain the self-renewal and tumorigenicity of glioblastoma stem-like cells and breast cancer stem-like cells." (PMID 22145042, 2011). "Similarly, aberrations in the PI3K/mTOR pathway, often due to loss of the tumor suppressor PTEN, further contribute to the malignancy of glioblastoma, facilitating uncontrolled cell growth and survival." (PMID 40650170, 2025). "Previous research has shown that compensatory cross-regulation of Erk and AKT/mTOR signaling may allow glioblastoma cells to proliferate unabated and escape cell death from trametinib treatment." (PMID 41428766, 2025). "Regardless of the original mutation leading to increased mTOR activity, mTOR plays a major role in the continued proliferation of glioblastoma." (PMID 40943615, 2025). "Additionally, phloridzin targets the PI3K/AKT/mTOR pathway, a key driver of glioblastoma progression, by suppressing PI3K, p‐AKT, and p‐mTOR expression, ultimately decreasing tumor cell survival." (PMID 40761486, 2025). "Moreover, activation of PI3K/Akt/mTOR signaling, increased glycolysis flow and lipid storage all have an effect on the metabolic processes in glioblastoma." (PMID 38479191, 2024). "Hispidulin is also reported to activate AMP-activated protein kinase (AMPK), thereby suppressing eukaryotic initiation factor 4E-binding protein (4E-BP1) via the rapamycin (mTOR) pathway in glioblastoma multiforme (GBM) cells, one of the most common and deadly types of brain cancer." (PMID 39713250, 2024). "A similar rationale has guided research interest in glioblastoma therapy towards PI3K/AKT/mTOR (phosphoinositide 3-kinase/ protein kinase B/ mammalian target of rapamycin) pathway inhibitors, which should impend cell survival and growth and regulate protein synthesis and cell metabolism." (PMID 39727987, 2024). "Furthermore, dysregulated mTOR activity promotes tumor growth of subependymal giant cell astrocytomas (SEGAs) in TSC as well as in cells from glioblastoma multiforme (GBM)." (PMID 39652154, 2024). "In glioblastoma, activation of the mTOR pathway contributes to cancer cell growth." (PMID 38583115, 2024). "In fact, subsequent inhibition of PRMT5 sensitised the glioblastoma cells to mTOR inhibition." (PMID 39703687, 2024).
glioblastoma (continued). "Furthermore, a recent study identified the expression of E2F7 activating the transcription of enhancer of zeste homolog 2 (EZH2), thus inducing mTOR signalling in glioblastoma progression." (PMID 39348343, 2024). "mTOR inhibition with rapamycin protected glioblastoma cells from temozolomide toxicity." (PMID 38182566, 2024). "Another research showed that bevacizumab, a standard chemo drug in glioblastoma treatment could increase the chemotherapy resistance of glioblastoma cells by elevating their autophagy levels, achieved through the suppression of the Akt-mTOR signaling pathway." (PMID 39201332, 2024). "Additionally, mTOR inhibitors and specific targeting of Rictor modifications have been very effective in experimental glioblastoma models." (PMID 37949943, 2023). "The mTOR inhibitor rapamycin and its analogs, commonly referred to as rapalogs, have been extensively explored as potential therapeutic agents for various diseases, including glioblastoma." (PMID 37834408, 2023). "Melatonin could be a potent therapeutic drug for glioblastoma by inducing apoptosis via the Akt/mTOR pathway." (PMID 38260850, 2023). "This could be particularly interesting in childhood glioblastoma and astrocytoma regarding described mTOR and mTORC2 hyperactivity in CNS malignancies." (PMID 37949943, 2023). "Furthermore, it seeks to assess the potential of targeting mTOR as a therapeutic approach for glioblastoma management." (PMID 37834408, 2023). "Nevertheless, the mTOR pathway plays a central role in glioblastoma pathogenesis." (PMID 37834408, 2023). "Consequently, ongoing advanced research is investigating additional potential biomarkers and developing targeted inhibitors that can accurately identify and efficiently target mTOR signaling, aiming to enhance the efficacy of glioblastoma treatment." (PMID 37834408, 2023). "Consequently, advanced research is actively exploring the potential of combination therapies involving targeted treatments and immunotherapies to augment the efficacy of mTOR inhibition in treating glioblastoma." (PMID 37834408, 2023). "In a 2014 study, experimental results revealed that the use of the cathepsin S inhibitor ZFL resulted in the upregulated expression of the autophagy-related protein LC3 and the phosphorylation of AKT, mTOR, and p70S6K in human glioblastoma cells, thereby promoting autophagy and apoptosis." (PMID 37398678, 2023). "Moreover, they established that the phosphorylated insulin-like growth factor-1 receptor (p-IGF-1R)/PI3K/AKT/mTOR signaling pathway was the target of Luteolin for reducing the migration of glioblastoma cells." (PMID 36992138, 2023). "Preclinical studies show that mTOR inhibitors effectively curb glioblastoma growth in mouse models." (PMID 37834408, 2023). "The integration of personalized medicine approaches can assist in determining the most effective treatment strategies based on individual patient profiles, thereby maximizing the therapeutic potential of mTOR targeting in glioblastoma and improving patient outcomes." (PMID 37834408, 2023). "The dysregulation of mTOR in glioblastoma highlights its significance as a therapeutic target." (PMID 37834408, 2023). "CCT4 may facilitate glioblastoma cell growth by involving the YB-1/CCT4/mLST8/mTOR signaling pathway." (PMID 37006287, 2023). "Furthermore, KDEL2R promotes the occurrence of glioblastoma by regulating the phosphorylation level of mTOR (Ser2448)." (PMID 37563735, 2023). "The exploration of precise mTOR-targeted therapies ultimately offers elevated therapeutic outcomes and the development of more effective strategies to combat the deadliest form of adult brain cancer and transform the landscape of glioblastoma therapy." (PMID 37834408, 2023).
glioblastoma (continued). "In glioblastoma, mTOR inhibitors may exhibit off-target effects and potential toxicities, particularly rapalogs and second-generation mTOR inhibitors." (PMID 37834408, 2023). "Glioblastoma patients with intact PTEN may respond better to mTOR inhibitors due to less hyperactivation of the pathway." (PMID 37834408, 2023). "The intricate interplay between the mTOR pathway and other signaling cascades in glioblastoma presents a challenging yet critical area of research aimed at developing effective and personalized therapeutic approaches for patients with this aggressive brain cancer." (PMID 37834408, 2023). "Furthermore, glioblastoma cells demonstrate altered nutrient sensing mechanisms contributing to mTOR activation." (PMID 37834408, 2023). "However, mTOR-mediated glioblastoma treatment faces limitations, including off-target effects, drug toxicity, poor bioavailability, drug resistance, and feedback activation of alternative signaling pathways." (PMID 37834408, 2023). "Over the years, researchers have conducted numerous clinical trials to assess whether mTOR inhibitors, either as monotherapies or in combination therapies, effectively and safely treat glioblastoma." (PMID 37834408, 2023). "Glioblastoma patients receiving mTOR inhibitors may experience gastrointestinal side effects, including nausea, vomiting, and diarrhea." (PMID 37834408, 2023). "A previous study showed that IDH1 could affect cell migration by modulating the PI3K/AKT/mTOR pathway in primary glioblastoma cells." (PMID 37324278, 2023). "Additionally, mTOR inhibitors have demonstrated the ability to induce autophagy, promoting tumor cell death and sensitizing glioblastoma cells to other therapeutic agents." (PMID 37834408, 2023). "Additionally, developing novel mTOR inhibitors with improved specificity and potency holds promise to overcome resistance and enhance treatment responses in glioblastoma and other cancers." (PMID 37834408, 2023). "Genetic alterations frequently observed in glioblastoma lead to the activation of the mTOR pathway." (PMID 37834408, 2023). "The YB-1/CCT4/mLST8/mTOR axis promotes glioblastoma growth in vivo." (PMID 35239512, 2022). "The mitochondrial damage caused glioblastoma cells to undergo autophagy preferentially by downregulating the expression of PARL and changing the ratio of BECN1/Bcl‐2 and the process of mitophagy was regulated by the PI3K/Akt/MAPK/mTOR/Ulk1 pathway." (PMID 34799992, 2022). "The YB-1/CCT4/mLST8/mTOR pathway is upregulated in patients with glioblastoma." (PMID 35239512, 2022). "Tissue-restricted mTOR inhibition enabled by this binary pharmacology strategy reduced the toxicity in peripheral tissues but maintained therapeutic benefits of RapaLink-1 in glioblastoma xenograft models." (PMID 36104566, 2022). "Additionally, clinical use of rapamycin can upregulate drug sensitivity in glioblastoma for its inhibition of mTOR signaling." (PMID 36010960, 2022). "Also, in glioblastoma, mTOR-specific inhibitor rapamycin and mTOR silencing were found able to completely disrupt the VM formation under both hypoxic and normoxic conditions." (PMID 36224457, 2022). "Inhibition of the tumorgenic EVs-mediated PI3K-Akt-mTOR pathway activation might be a novel strategy to shed light on glioblastoma therapy." (PMID 35022057, 2022). "Reduction of YB-1 in glioblastoma cells inhibits mTOR signaling." (PMID 35239512, 2022). "Interestingly, the KDEL receptor (KDELR2) can also target and promote the growth of HIF1a through the mTOR signaling pathway to guide glioblastoma." (PMID 36474171, 2022). "Similarly, curcumin was reported to suppress tumorigenic features in CSCs from glioblastoma and liver cancer by acting on mTOR-dependent Atg activation." (PMID 35897685, 2022). "Also in glioblastoma, Palbociclib administration induced an early suppression of downstream mediators of mTOR, like S6, and, as rebound effect, an increased mTOR activity." (PMID 35712501, 2022).
glioblastoma (continued). "Elevated mRNA expression may lead to increased active 4EBP1 protein levels in glioblastoma, as it was reported that mTOR activity is reduced regionally in this tumor entity, thus leading to 4EBP1 activation in poorly vascularized areas." (PMID 35228525, 2022). "While PI3K gain-of-function mutations were detected in 25% of patients suffering from glioblastoma, the main negative regulator of the PI3K/AKT/mTOR pathway, the phosphatase and tensin homolog (PTEN), is deleted or affected by loss-of-function mutations in 40% of the cases." (PMID 36013437, 2022). "Multiple signaling pathways, such as the Wnt signal, the phosphatidylinositol 3-kinase (PI3K)/Akt/mammalian target of rapamycin (mTOR) axis, and the programmed death (PD)-1 and PD-ligand 1 (PD-L1) axis, are reported to participate in regulating the proliferation of human glioblastoma cells." (PMID 36013056, 2022). "PI3K/Akt/mTOR signaling pathway and Wnt/β-catenin signaling pathway are two essential regulation pathways for glioblastoma, found to be activated excessively under pathological conditions functioning to mediate cell proliferation, EMT process, apoptosis, autophagy, metabolism and angiogenesis." (PMID 36234681, 2022). "Similarly, a combination of CQ and NVP-BEZ235, an inhibitor of the PI3K/mTOR pathway, led to apoptosis in several glioblastoma cell lines in vitro and a growth reduction in glioblastoma xenografts in vivo." (PMID 36294938, 2022). "Thus, we corroborated that mTOR inhibition was relevant in the context of clinical glioblastoma treatment and that this was correlated with EMT and stemness modulation in the respective tumor models." (PMID 34575669, 2021). "Thus, there is a possibility that AdipoR2 inhibits human glioblastoma cell growth through the AMPK/mTOR pathway." (PMID 33752745, 2021). "We used to find that inhibition of CTSS in glioblastoma cell lines could suppress the PI3K/AKT/mTOR pathway in previous study." (PMID 33613746, 2021). "In the previous study, we found that the application of CTSS inhibitors in glioblastoma cell lines could down-regulate the activated state of PI3K/AKT/mTOR pathway." (PMID 33613746, 2021). "Interestingly, palbociclib did not have any significant direct effects on mTOR signalling as a single agent in DMGs, in contrast to its actions on mTOR observed in glioblastomas." (PMID 34944870, 2021). "Hence, one possible mechanism explaining the CoCl2-induced reduction in levels of phosphorylated mTOR in TMZ-resistant glioblastomas is due to disruption of the PI3K-AKT pathway." (PMID 34136065, 2021). "Furthermore, the combination of TMZ with resveratrol affected the activation of AMPK and inhibited mTOR (the mechanistic target of rapamycin), leading to apoptosis of glioblastoma cells." (PMID 34204594, 2021). "However, the combination with an mTOR inhibitor has been suggested as a viable combination strategy for treating recurrent glioblastomas." (PMID 34572040, 2021). "Indeed, the interactome of ERβ5 has been described in glioblastoma cells, and it has been revealed that this receptor can interact with mechanistic target of rapamycin kinase (mTOR) or eIF-2-alpha kinase activator GCN1 to promote cell migration and invasion." (PMID 34068748, 2021). "Taken together, our results demonstrated that inhibition of CTSS could reverse TGF-β-mediated EMT and tight junction proteins turnover in human glioblastoma cell lines through suppressing the PI3K/AKT/mTOR pathway." (PMID 33613746, 2021). "In addition, a study on glioblastomas found that mTOR inhibitors were able to reverse the increased mTOR signalling triggered by CDK4/6 inhibitors, with this compensatory relationship suggesting a promising potential combination therapy." (PMID 34944870, 2021). "In addition, in the same study in vitro experiments revealed the ability of these compounds to potently induce autophagy in human glioblastoma cell lines (U87MG) via inhibition of mTOR phosphorylation by the PI3K-AKT-mTOR pathway." (PMID 32110992, 2020).
glioblastoma (continued). "Additionally, the mTOR signaling pathway is positively correlated with Ki-67 expression and rapamycin was found to inhibit Ki-67 expression in patients with glioblastoma." (PMID 32517736, 2020). "mTOR inhibitors-resistant glioblastoma cells have a compensatory increase in glutamine metabolism, suggesting that combined inhibition of GLS1 and mTOR could potentially overcome resistance." (PMID 32211323, 2020). "Moreover, aberrant activation of PI3K/Akt/mTOR pathway has been correlated with poor prognosis in glioblastoma patients." (PMID 32463592, 2020). "In the present study, E2F7 triggered the AKT/mTOR pathway by inhibiting PTEN in glioblastoma." (PMID 32814835, 2020). "Therefore, inhibition of the PI3K/Akt/mTOR signaling pathway has been widely investigated as a potential therapy for cancer including glioblastoma." (PMID 33718332, 2020). "Mammalian target of rapamycin (mTOR) is upregulated in a high percentage of glioblastomas." (PMID 33162811, 2020). "Berberine in combination with solid lipd curcumin particles could also increase cell death by inhibiting PI3K/Atk/mTOR pathway in glioblastoma cells." (PMID 33362566, 2020). "In our previous work, we demonstrated that autophagy induction by nutrient starvation or by mTOR inhibition impairs migration and invasion in glioblastoma cells through reversing the Epithelial-to-Mesenchymal Transition (EMT) process and inhibiting the Wnt/β-catenin pathway." (PMID 32823532, 2020). "Furthermore, radiation can also activate mTOR signaling in vascular endothelium and in glioblastoma cell lines." (PMID 33718332, 2020). "In this regard, results from the EORTC 26082 trial suggest that a subgroup of glioblastoma patients might be eligible for treatment with mTOR inhibitors." (PMID 31510109, 2019). "Therefore, glioblastoma cells from the lines U87 and T98G were exposed to carnosine, to the mTOR inhibitor rapamycin and to the PI3K inhibitor Ly-294,002." (PMID 31247000, 2019). "Here, we asked whether carnosine (β-alanyl-L-histidine), a naturally occurring dipeptide, exert its anti-neoplastic effect on glioblastoma cells via PI3K/Akt/mTOR signaling." (PMID 31247000, 2019). "Any functional irregularity in mTOR has been shown to be involved in the development of glioblastoma, and thus it has been suggested that mTOR signaling pathway inhibition may have therapeutic value in this disease." (PMID 31013819, 2019). "Dysregulation of mTOR was found in different types of tumors including glioblastoma." (PMID 31179240, 2019). "Random patient selection without prior testing for exclusion of patients with tumors without mTOR activation may be responsible for the poor response found in the recent RTOG 0193 trial for glioblastoma patients treated with an mTOR inhibitor." (PMID 31258848, 2019). "Stellettin B has been demonstrated to cause cell death through the inhibition of the PI3K/Akt/mTOR pathway, which generates reactive oxygen species in SF295 glioblastoma cells, and the induction of mitochondria-related apoptosis through the inhibition of K562 human chronic myeloid leukemia cells." (PMID 30769863, 2019). "Specifically, NC inhibited the phosphorylation of Akt and mTOR in glioblastoma cells." (PMID 30847386, 2019). "Furthermore, FTY720-induced inhibition of the PI3K/AKT/mTOR/p70S6K signaling pathway was shown to suppress migration and invasion in human glioblastoma cell lines." (PMID 29467620, 2018). "And YAP expression levels seemed to be correlated with the phosphorylation levels of mTOR, p70S6K, and 4E-BP1, implying that mTOR signaling pathway might be an important regulator in controlling YAP expression in glioblastoma cells." (PMID 29780826, 2018). "Bevacizumab could suppress Akt-mTOR signaling pathway to induce high level of autophagy in glioblastoma cells." (PMID 30455420, 2018). "Moreover, studies investigated the role of Akt and mTOR in maintaining the integrity of CSCs in different malignancies, including glioblastoma and neuroblastoma." (PMID 30323898, 2018).